E2F2 (E2F transcription factor 2)
Diseases named in the same sentence as E2F2 in open-access papers (continued):
Sharing a sentence is not in itself a finding about the gene and the disease.
teratocarcinoma (1 paper, 2013). A germ cell tumor characterized by the presence of an embryonal carcinoma component and a teratoma component. "They reported that human stem cells and teratocarcinoma cells show a selective reduction in the expression of E2F1, E2F2, E2F3 and p105 (encoded by NFKB1) and enhanced expression of E2F4, E2F5, E2F6 and p130 (encoded by RBL2) compared with human normal somatic IMR90 cells." (PMID 24355041, 2013).
thymic lymphomas (1 paper, 2021).
triple-negative breast carcinoma (1 paper, 2020). An invasive breast carcinoma which is negative for expression of estrogen receptor (ER), progesterone receptor (PR), and human epidermal growth factor receptor 2 (HER2). "More importantly, our studies led to the discoveries of new potential therapeutic targets, such as E2F2, as well as a novel drug-induced targeting of estrogen receptor β (ESR2) approach for triple-negative breast cancer treatment, currently lacking of targeted therapies." (PMID 32678032, 2020).
viral infections (1 paper, 2018). "Other members of the network also reappeared in the gene set enrichment analysis as members of pathways associated with viral infections (DDX58, IFIT1, IRF1, MX1, STAT1) or viral carcinogenesis and cell cycle (CCND1, CCND3, CCNE1, CDC20, E2F2, RANBP1)." (PMID 30042828, 2018).
ZIKV infection (1 paper, 2017). "One recent study reported that several apoptotic regulators, including ZMAT3, PMAIP1, TNFRSF10D, BBC3, were upregulated, and cell cycle genes, such as E2F1 and E2F2, were downregulated after ZIKV infection." (PMID 29116029, 2017).
tumor (137 papers, 2006 to 2026). "The up-regulation of miR-155 has been shown to increase proliferation and invasion potential of ccRCC tumour cells in vitro and was found to be associated with clinical aggressiveness through the targeting of E2F2 and JADE-1." (PMID 38999991, 2024). "E2F2, in addition to its capacity to facilitate tumor progression, has also been implicated in the suppression of tumor growth through specific mechanisms." (PMID 38807594, 2024). "Furtherly, multivariate Cox regression showed T stage, N stage, pathologic stage, E2F2 expression level, age and residual tumor were independent risk factors for unfavorable survival (OS) of CRC patients." (PMID 35069909, 2022). "The retarded tumor growth in the sh-circPTN group was associated with a reduced E2F2 level and an increased miR-432-5p level in the xenograft tumors." (PMID 36249712, 2022). "The transcription levels of E2F1/3/5/8 are obviously up-regulated in PAAD and the high expression of E2F2/3/6/8 was apparently associated with the tumor stage of patients with PAAD." (PMID 33604289, 2020). "E2F2 worked as an activator in the tumor invasion of NSCLC, and it was implicated in the proliferation and poor prognosis of NSCLC cells." (PMID 32598517, 2020). "In this study, we use IHC method to analysis 52 nonkeratinizing NPC tissues and 34 NPG tissues revealed stronger E2F2 expression in the former, which was associated with the clinical tumor stage." (PMID 31467515, 2019). "This association supports the results obtained from the mice tumours that pointed out that lower expression of E2F2 and EMR2 proteins (due to miR-99a upregulation) favours an epithelial phenotype and downregulation of stemness-associated genes." (PMID 29072692, 2017). "The loss of IFI6 results in E2F2-mediated dysregulation of DNA replication, resulting in cellular senescence or apoptosis and tumor growth inhibition." (PMID 27608486, 2016). "To explore molecular mechanisms underlying miR-31-mediated tumor-suppression, we examined the expression of E2F2 and STK40, two known downstream target oncogenes for miR-31." (PMID 25568668, 2014). "Since the encoded E2F2 transcription factor has been implicated in both tumor suppression and tumor development, we conducted a functional study to investigate the pertinence of E2F2 to human gliomagenesis." (PMID 25202354, 2014). "Most importantly, E2f2 deficiency accelerates tumor onset in the T cell model as it does for the Eμ-myc model." (PMID 19749980, 2009). "Our gene expression data supports this hypothesis and low E2F2 activity is associated with a highly unstable tumor." (PMID 33087787, 2020). "Although many recent studies have associated E2F2 activity with inappropriate cell proliferation and/or apoptosis in various tumor types, the role of E2F2 in NPC remains unknown." (PMID 31467515, 2019). "Indeed, we saw that loss of E2F2 increased time to tumor onset by an average of 160 days (p = 0.0057)." (PMID 26474282, 2015). "However, only the loss of E2F2 significantly increased the percentage of tumor bearing mice with metastasis to the lung to 67% (p = 0.0361)." (PMID 26474282, 2015). "We found that tumor emergence was accelerated by E2F2 loss and delayed by E2F4 loss." (PMID 19749980, 2009). "Additionally, E2F2 has been shown to be associated with the efficacy of some anti-tumor drugs, indicating that it may serve as a new candidate for targeted cancer therapy." (PMID 38807594, 2024). "In addition, other aspects of their findings are reminiscent of our results, namely that E2f2 heterozygotes have an intermediate phenotype, suggesting some haploinsufficiency, and that with E2f2 deficiency there is an increased incidence of multiple tumor clones." (PMID 19749980, 2009).
tumor (continued). "In the control group, E2F2 was highly expressed in clusters of small, round cells located at the tumor margins and between tumor masses." (PMID 40316727, 2025). "Drives steatosis, lipotoxicity, cell apoptosis, and tumor cell survival in hypoxic environments; linked to genetic mutations (e.g., E2F1/E2F2 activation)." (PMID 41262444, 2025). "In recent decades, in-depth research on E2F2 in cancer has elucidated E2F2 functions in tumor-cell metabolism, anti-angiogenesis, metastasis, therapy resistance, and tumor immunoediting." (PMID 38807594, 2024). "In the future, with the in-depth understanding of the functional mechanism and regulatory network between miRNA and E2F2, their importance in tumor therapy and diagnosis will be further confirmed and played." (PMID 38807594, 2024). "We further examined the relative RNA levels of circSTRBP, miR‐1294, miR‐593‐3p and E2F2 in tumour tissues." (PMID 38520208, 2024). "In mice xenografts of neuroblastoma cells stably expressing doxycycline-inducible DOT1L shRNA, ablating DOT1L expression with doxycycline significantly reduced ODC1 and E2F2 expression, reduced tumor progression, and improved overall survival." (PMID 38807594, 2024). "used a bitransgenic mouse model of Myc-induced T cell lymphomagenesis and analyzed tumor progression in mice deficient for E2F1, E2F2, or E2F3." (PMID 38807594, 2024). "Unexpectedly, the up-regulated miR-5100 target genes (CCNE2, E2F1, E2F2) had higher levels of expression in the tumor samples." (PMID 39590378, 2024). "A multitude of studies have repeatedly shown that blocking E2F2 activity limits tumor cell proliferation and viability due to the promoting role of E2F2 in tumor progression." (PMID 38807594, 2024). "Compared with the exo‐si‐NC samples, tumour tissues from the exo‐si‐circSTRBP group expressed lower levels of circSTRBP and E2F2 and the increased levels of miR‐1294 and miR‐593‐3p (p < 0.05)." (PMID 38520208, 2024). "Prominent discoveries revealed heightened regulon activities of the E2F family (E2F1, E2F4 and E2F2), which are crucial in promoting tumour growth and migration." (PMID 39187937, 2024). "In recent years, extensive research has confirmed the significant role of E2F2 in tumor progression, which can exert pro-cancerous or anti-cancerous effects depending on its specific context." (PMID 38807594, 2024). "These contradictory results appear to be related to the bidirectional regulation of the cell cycle, and current evidence suggests that E2F2’s role as a tumor suppressor or tumor promoter depends on the cellular context and its interaction with other E2Fs." (PMID 38371373, 2024). "In the 80 pairs of GC tumour and normal specimens, E2F2 mRNA showed an upregulation in the cancerous tissues (p < 0.001)." (PMID 38520208, 2024). "In this study, we demonstrated that the median protein concentration of E2F2 was higher in HPV-negative patients in the tumour tissues (0.193 vs. 0.056; p-value = 0.03)." (PMID 37185737, 2023). "The median E2F2 relative gene expression in the tumour was 0.263 (0.145–0.578) and 0.47 (0.051–0.784) in the margin." (PMID 37047293, 2023). "This is the first study to evaluate the levels of E2F2, MDM2 and p16 in the primary OSCC tumour and the matching margin samples and their association with the selected sociodemographic and clinicopathological characteristics." (PMID 37185737, 2023). "Patients with N0 had a significantly lower E2F2 concentration than patients with N1 (0.125 vs. 0.373; p-value = 0.02) in the tumour samples." (PMID 37185737, 2023). "We found that patients with N0 showed significantly lower E2F2 concentrations than patients with N1 in the tumour samples and the median protein concentration of E2F2 was higher in HPV-negative patients in the tumour samples." (PMID 37185737, 2023). "Higher E2F2 protein concentrations were also noted in patients with N3 compared to N0 in tumour samples." (PMID 37185737, 2023).
tumor (continued). "Still, we found a higher expression of E2F2 gene in the margin samples, while E2F2 protein level was higher in the tumour specimens." (PMID 37047293, 2023). "While the median E2F2 protein level in the tumour was 0.129 ng/μg (0.051–0.238) and 0.082 ng/μg (0.047–0.282) in the margin." (PMID 37047293, 2023). "The patients with N0 had a significantly lower protein level of E2F2 than patients with N3 (0.125 vs. 0.581; p-value = 0.022) in tumour samples." (PMID 37047293, 2023). "The patients with T1 had a significantly higher gene expression level of E2F2 than patients with T2 (0.581 vs. 0.237; p-value = 0.019) and T3 (0.581 vs. 0.145; p-value = 0.004) in tumour samples." (PMID 37047293, 2023). "E2F2, as an important member of E2F family, has attracted growing research attenttion in tumorigenensis and tumor progression in different malignancies." (PMID 35069909, 2022). "The patients with G2 tumours had a significantly higher gene expression level of E2F2 than patients with low-grade G1 tumours." (PMID 36551770, 2022). "In the univariate analysis, T stage, N stage, M stage, pathologic stage, age, E2F2 expression level and residual tumor affected the prognosis of CRC patients (all p < 0.05)." (PMID 35069909, 2022). "In short, Exo silenced E2F2 in tumor tissues via transporting miR-631 to restrain NSLCL tumor advancement." (PMID 35353027, 2022). "The patients with G2 (moderately differentiated) tumours had a significantly higher gene expression level of E2F2 than patients with low-grade G1 (well-differentiated) tumours (p-Value = 0.031) in tumour samples." (PMID 36551770, 2022). "E2F2 is regarded as an oncogene in several types of malignant tumors, however, it can also be designated as a tumor suppressor gene." (PMID 35069909, 2022). "It is also worth emphasizing that patients with G2 (moderately differentiated) tumours had a significantly higher gene expression level of E2F2 than patients with low-grade G1 (well-differentiated) tumours." (PMID 36551770, 2022). "Compared with the control group, overexpression of E2F2 significantly increased the tumor growth in nude mice, while knockdown of E2F2 completely abolished tumorigenesis, indicating that E2F2 is essential for and can promote tumor growth in vivo in LUAD." (PMID 35844795, 2022). "We carried out immunohistochemistry staining for E2F2 in 102 paraffin-embedded human CRC tumor tissues, in which 26 cases were at pathological stage I, 32 cases at stage II and 44 cases at stage III." (PMID 35069909, 2022). "Previous studies indicated that E2F2 exhibited as a tumor suppressor in epithelial tissues or Myc-induced T cell lymphomagenesis, and overexpression of E2F2 inhibited the progression of these tumors." (PMID 35371973, 2022). "Overall, these data support the notion that E2F2 acts as an oncogenic transcription factor downstream of circPTN, which promotes proliferation and tumor progression in NSCLC cells." (PMID 36249712, 2022). "The E2F2 protein is a transcription factor that has a substantial function in controlling the action of the tumor suppressor proteins and the cell cycle." (PMID 35449091, 2022). "The aim of this study was to examine the possible association between CDKN2A, MDM2, E2F2 and LTF mRNA expression in the OSCC tumour and margin samples and influence on clinical variables in the Caucasian Polish population." (PMID 36551770, 2022). "Cell cycle activator E2F transcription factor 2 (E2F2) play a key role in tumor development and metastasis." (PMID 35003347, 2021). "Subgroup analysis based on age, sex, tumor grade and disease stage showed that E2F2 expression in GC patients was significantly higher than that in the normal control group." (PMID 34091441, 2021). "Studies analyzing expression and functional impact of E2F2 in these tumor types are underway, which will provide insight into the feasibility of targeting E2F2 to sensitize cancer cells to Fas/FasL-mediated apoptosis." (PMID 35008734, 2021).
tumor (continued). "Using a large number of independent datasets, we confirmed that E2F2 expression was significantly increased in GC tissues compared with non-tumor gastric tissues." (PMID 34091441, 2021). "In the subgroup analysis based on sex, age, race, disease stage, and tumor grade, E2F2 expression in GC patients was significantly higher than that in normal controls." (PMID 34091441, 2021). "The detail mechanism of ZNF750 on tumor suppressing in OSCC involved by E2F2 will be further investigated in the future." (PMID 35003347, 2021). "qRT-PCR indicated that miR-146b-3p in nude mice tumor tissues increased evidently, while E2F2 decreased evidently." (PMID 34433131, 2021). "This study revealed that E2F2 is overexpressed in GC, and the high level of E2F2 expression is related to the malignant biological behavior of the tumor and the poor prognosis of the patients." (PMID 34091441, 2021). "The expression of E2F2 was also decreased in xenograft tumor tissues of lncRNA RCAT1 knockdown group as determined by immunohistochemistry (IHC) and qRT-PCR assays." (PMID 34244473, 2021). "Using multidimensional analysis, we evaluated the E2F2-related genomic alterations and functional networks in GC and explored their roles in tumor immunity." (PMID 34091441, 2021). "E2F2 expression was predominantly elevated in NSCLC tumours and was also shown to correlate with cell proliferation leading to tumour progression." (PMID 33273537, 2020). "In the miRNAs that are downregulated in RB, miR-let-7a, a tumor suppressor, inhibits cellular proliferation and suppresses tumor growth by inhibiting E2F2 in osteosarcoma cells." (PMID 32992741, 2020). "The high expression of E2F2/3/6/8 can also be used as molecular markers to classify tumor stages in PAAD patients." (PMID 33604289, 2020). "HeLa and C-33 A cells were cultured in serum-free medium for 5 days for spheroid formation, and we found that the diameter of tumor microspheres in sh-E2F2- and sh-E2F7-transfected HeLa and C-33 A cells was shorter than that found in the control group." (PMID 33061852, 2020). "Previous studies have shown that E2F2 is an oncogene in many tumor types, for instance, it has been discovered that E2F2 is prominently up-regulated in NSCLC, and can be serve as a therapeutic target to prevent the proliferation and invasion of NSCLC." (PMID 33115417, 2020). "Previous studies indicated that like E2F1, E2F2 exhibited oncogenic or tumor suppressive activity, and overexpression of E2F2 contributed to the development of several solid tumors, indicating worse patient outcome." (PMID 30967995, 2019). "Consistent with these in vitro data, knocking down JMJD6 reduces E2F2 and Myc expression, suppresses tumor progression, and improves survival in mice." (PMID 31346162, 2019). "Our analysis suggested that let7c-5p-NRAS and miR-125b-5p-E2F2/E2F3 are several tumor suppressive pathways in HBV-related HCC." (PMID 30602391, 2019). "Potentially, PPAR-γ partly downregulates the expression of E2F2 and thus slows the proliferation of tumor cells." (PMID 31467515, 2019). "Some miRNA, such as MIRLET7A, act as tumour suppressors by targeting genes (e.g. E2F2), that enhance tumour growth." (PMID 30616540, 2019). "MiR-214 regulates tumor progression by targeting mRNAs encoding proteins such as poly(rC) binding protein-2 (PCBP2), E2F transcription factor 2 (E2F2), and the SUMO-conjugating enzyme UBC9." (PMID 29862267, 2018). "Micro RNA-155 and miRNA-210, amongst others, were reported to modulate the tumor microenvironment, regulate glucose metabolism, and target transcription factor E2F2 in ccRCC tumor cells." (PMID 30380599, 2018). "We also demonstrated that E2F2 expression was significantly correlated with tumor stage in patients with LC." (PMID 29754146, 2018). "E2F2 is a tumor suppressor that inhibits the cell cycle, while STK40 acts as a negative regulator of NF-kB-mediated transcription." (PMID 28783765, 2017).